ARHGAP24 (Rho GTPase activating protein 24)
Diseases named in the same sentence as ARHGAP24 in open-access papers (continued):
Sharing a sentence is not in itself a finding about the gene and the disease.
tumor (continued). "In conclusion, our results indicated that through crosstalk of tumor and leukocyte in BCa, ARHGAP17 and ARHGAP24 correlate with a tumor-promoting microenvironment through regulating CD8 + T cells and Treg infiltration and T cell function." (PMID 34307347, 2021). "Several RhoGAPs, including deleted in liver cancer 1 (DLC1) 6, ARHGAP24 7, ARHGAP26 8, and ARHGAP10 9, appear to function as tumor suppressors." (PMID 33994864, 2021). "Lower Th1/Th2 cell ratio, higher DC cell infiltration, and higher Treg cell infiltration were observed in ARHGAP17, ARHGAP24, and ARHGAP37 (STARD13), indicating a tumor-promoting microenvironment." (PMID 34307347, 2021). "Remarkably, in the TCGA‐LGG and GTEx cohorts, a significant majority of the ARHGAP family genes, with the exception of ARHGAP15, ARHGAP20, ARHGAP24, and ARHGAP28, exhibited notable differential expression between tumour tissues and normal samples, as established through Wilcoxon test analysis." (PMID 39075640, 2024). "We compared different clinicopathological features of HCC patients and found that ARHGAP24 downregulation was significantly correlated with satellite lesions (P = 0.031), CNLC stage (P = 0.020), microvascular invasion (P = 0.001) and tumor recurrence (P = 0.002)." (PMID 36168627, 2022).
cancer (12 papers, 2008 to 2024). A tumor composed of atypical neoplastic, often pleomorphic cells that invade other tissues. "Specifically, we found a significantly positive correlation of ARHGAP24 expression with the stromal score in pan‐cancer, whereas it was negatively associated with RNAss." (PMID 33463006, 2021). "Mechanistically, circ-LMO7 was packed in exosomes and acted as a cancer-suppresser on OS by sponging miR-21-5p and upregulating the expression of ARHGAP24." (PMID 38742566, 2024). "The results revealed that knockdown of ARHGAP24 increased the numbers of migrating and invading cancer cells, while ARHGAP24 overexpression decreased these cells." (PMID 36168627, 2022). "When ARHGAP24 is highly expressed in cancer cells, it may recruit WWP1 to form protein complexes and then promote PKM2 degradation." (PMID 36168627, 2022). "In addition, in vivo and in vitro experiments showed that high ARHGAP24 levels could inhibit cancer cell proliferation, migration and invasion." (PMID 36168627, 2022). "Over the past decades, several key regulators were revealed to modulate cancer cell proliferation, cell cycle, and apoptosis in NSCLC, such as NUP37, ARHGAP24, and PTEN." (PMID 34351079, 2021). "HeLa cell lysate was also used in the other western blots, with expression of ARHGEF1, ARHGEF11, ARHGEF12, ARHGAP5, ARHGAP24 and ARHGDIA protein reported in this cancer cell line." (PMID 18190708, 2008). "The direction of the altered expression of LIFR, ARHGAP24, and CNTNAP2 varied in each cancer type." (PMID 33463006, 2021). "Six of the 10 remaining genes, despite not being listed, were genes for which literature search supported undeniable oncogenic properties (STIM2, ARHGAP24, KLF12, KMT2C, CCDC88C and DOCK11), and 4 genes were—to our knowledge—not previously reported in cancer, yet may include new candidate drivers." (PMID 28534499, 2017).
infection (2 papers, 2022 to 2025). The state of being infected such as from the introduction of a foreign agent such as serum, vaccine, antigenic substance or organism. "It is of note that there were six proteins (Chm, Tgm3, Arhgap24, Tanc1, Agap1, Pnkd) that were uniquely expressed on the third day after infection." (PMID 36061859, 2022). "Additionally, genes such as DOCK2, ARHGAP24, and KCTD18 regulate cytoskeletal reorganization and cell migration, ensuring that immune cells effectively reach infection or inflammation sites." (PMID 40098976, 2025).
kidney disease (2 papers, 2021 to 2025). "In addition to Arhgap24, Srgap1, and the other GTPase-activating proteins, other genes involving small GTPase-mediated pathways may also mediate miR-145-5p-induced podocyte injury (e.g., PLCE1, which mutations have been shown to cause podocyte injury and kidney diseases)." (PMID 34729245, 2021).
ARHGAP24 also shares sentences with these, for which no sentence is quoted: melanoma (4 papers); astrocytoma (2); glioblastoma (2); lymphoma (2); Alzheimer’s dementia (1); atrial fibrillation (1); B-cell lymphomas (1); chronic kidney disease (1); colorectal cancer (1); congenital nephrotic syndrome (1); diffuse large B-cell lymphoma (1); follicular lymphoma (1); glaucoma (1); hypoplastic left heart syndrome (1); lung adenocarcinoma (1); minimal change disease (1); osteosarcoma (1); pancreatic ductal adenocarcinoma (1); pulmonary hypertension (1); Tetralogy of Fallot (1); type 1 diabetic (1).